STAT3 (signal transducer and activator of transcription 3)
Diseases named in the same sentence as STAT3 in open-access papers (continued):
Sharing a sentence is not in itself a finding about the gene and the disease.
gastric cancer (continued). "Constitutively activated STAT3 promotes cell proliferation and survival in many cancers including breast, brain, colon, prostate, lung, pancreatic, gastric cancers, and so on." (PMID 28883791, 2017). "Thymoquinone's inhibition of STAT3 phosphorylation, associated with reduction in JAK2 and c-Src activity, as well as Bcl-2, cyclin D, survivin, and VEGF was also reported in gastric cancer cells." (PMID 28881699, 2017). "Mechanism researches suggested that SIRT1 can counteract the activation of STAT3 and NF-κB to repress cell growth and lead to G1-phase arrest via NF-κB/Cyclin D1 signaling in gastric cancer." (PMID 29088792, 2017). "BBR and CUR will synergize with 5FU and target STAT-3 which can lead to sensitivity to 5FU in gastric cancer cells." (PMID 28611316, 2017). "Subsequently, we confirmed overexpression of STAT3 can enhance the CD163 level in gastric cancer cells." (PMID 29152078, 2017). "The interaction of Notch, STAT3 and Twist signaling in gastric carcinoma is reported to have an important function in promoting the development of gastric cancer." (PMID 28881855, 2017). "In xenograft model of gastric cancer mice, thymoquinone showed anticancer activity by down-regulating STAT3 pathway." (PMID 28881699, 2017). "shRNA-mediated B7-H3 silencing in the N87 gastric cancer cell line suppressed cell migration and invasion in vitro and in vivo; downregulated metastasis-associated CXCR4; and inhibited AKT, ERK, and Jak2/Stat3 phosphorylation." (PMID 29069741, 2017). "Predominantly, the SIRT1, STAT3, and pSTAT3 proteins were detected in the nucleus of gastric cancer tissues and rarely in the cytoplasm." (PMID 28061480, 2017). "Knockdown of CMTM3 promoted metastasis of gastric cancer via the STAT3/Twist1/EMT signalling pathway." (PMID 29213215, 2017). "Totally, all these findings confirmed that STAT3 was an important regulator of CD163 in gastric cancer cells." (PMID 29152078, 2017). "The increase of VEGF expression has also been detected in gastric cancer, which is stimulated by IL-17 in a STAT3 dependent manner." (PMID 28978186, 2017). "In contrast, adding IL-6 neutralizing antibody or JAK-2 protein tyrosine kinase inhibitor AG490 into the co-culture system significantly reversed CAF-mediated phosphorylation of JAK2 and STAT3 in gastric cancer cells." (PMID 28186964, 2017). "STAT3 remains constitutively activated in several human cancers including gastric cancer during cell proliferation, cell survival, immune evasion and inflammation." (PMID 28061480, 2017). "IL-6 treatment activates the gp130/STAT3 pathway in gastric cancer cells to up-regulate MUC4, which can be detected at early stages of the gastric carcinogenetic process." (PMID 28978186, 2017). "Persistently-active STAT3 was found in several gastric cancer cell lines, where it serves a key mediator of cancer growth and metastatic potential." (PMID 29383166, 2017). "RelA expression in gastric cancer tissue strongly correlated with abundance of other tumor- and metastasis-promoting markers, including STAT3, MMP-9, IL-6 and VEGF." (PMID 28350359, 2017). "From clinical gastric cancer specimens, the expression of Notch1 and Jagged1 are tightly correlated with the phosphorylation level of STAT3 and the expression level of Twist." (PMID 28881855, 2017). "One early study observed that viral latent membrane protein 2A (LMP2A) increased DNMT1 expression, and that knockdown of STAT3 by siRNA counteracted LMP2A-mediated DNMT1 expression in gastric carcinoma cells." (PMID 28360411, 2017). "Our group found that TGR5 is a suppressor of gastric cancer cell proliferation and migration through antagonizing STAT3 signaling pathway." (PMID 28082913, 2016). "Our study demonstrated that Sal exerts antiangiogenic activity in vitro and in vivo through blocking VEGFR2/STAT3 pathway in endothelial cells, suggesting that STAT3 is a potential target of Sal in gastric cancer cells." (PMID 27058891, 2016).
gastric cancer (continued). "Overall, this study demonstrates that knockdown of CMTM3 promotes the metastasis of gastric cancer through the STAT3/Twist1/EMT pathway." (PMID 27121055, 2016). "For the molecular mechanisms, CDDP alone increased the cancer stem cell (CSC)-like properties in gastric cancer cells via activating the interleukin-6 (IL-6)/IL-6 receptor (IL-6R)/signal transducer and activator of transcription 3 (STAT3) signaling." (PMID 27824145, 2016). "In our study, we show that Cu-I markedly inhibits gastric cancer cell growth by inducing G2/M phase cell cycle arrest and apoptosis at low nanomolar concentrations via a STAT3-independent mechanism." (PMID 26890145, 2016). "Especially, chronic STAT3 activation was reported to serve as a key promoter in the induction and progression of gastric cancer." (PMID 27917904, 2016). "Determining the potential role of the STAT3 inhibitor in the treatment of gastric cancer is worthy of further investigation." (PMID 27598141, 2016). "Since Sal suppressed the activation of STAT3 and STAT3-regulated proliferative gene products, we further explored the antiproliferative activity of Sal, a broad of gastric cancer cell lines were treated with serial concentrations of Sal by the MTS assay." (PMID 27058891, 2016). "LMP2A, another EBV protein, was also shown to activate STAT3 in gastric cancer cells and fibroblasts." (PMID 27458446, 2016). "Activation of STAT3 was previously found to associate with drug resistance in GC50, and derepression of NR4A3 sensitized gastric cancer cells to cisplatin." (PMID 27528092, 2016). "The activation of STAT3 promotes gastric cancer progression, suppresses apoptosis and promotes invasion." (PMID 27052330, 2016). "In this study, we examined the role of STAT3 in the expression and methylation of its targets in gastric cancer patients." (PMID 27598141, 2016). "To address such a possibility, we examined the inhibitory effect of Sal on STAT3 in human gastric cancer SGC-7901 cells." (PMID 27058891, 2016). "In this study, we found that the expression level of GATA6 is inversely correlated with that of STAT3 in gastric cancer patients." (PMID 27598141, 2016). "Taken together, knockdown of CMTM3 promoted cell migration though the STAT3/Twist1/EMT pathway in gastric cancer." (PMID 27121055, 2016). "The interleukin-6 (IL-6)/JAK/STAT3 signaling pathway plays a central role in inflammation-mediated cancers, including gastric cancer (GCa)." (PMID 27049718, 2016). "Previous study has reported that gastrin acting on CCK-BR induces cyclooxygenase-2 expression through JAK2/STAT3/PI3K/Akt pathway in human gastric cancer cells." (PMID 27518872, 2016). "Recently, many new insights into the core signaling pathways in gastric cancer have been made, including STAT3 and Akt pathways." (PMID 27518872, 2016). "Based on the findings of the current study, it is necessary to analyze the relationship among CMTM3, p-STAT3, Twist1 expression and metastasis in gastric cancer." (PMID 27121055, 2016). "Theseresults suggest that the silencing of Ass1 expression reduces STAT3 expressionin human gastric cancer cell lines." (PMID 25928182, 2015). "The coupling of the PI3K/Akt signaling blocking and STAT3 activation is an important event that promotes survival of the resistant gastric cancer cells in the presence of trastuzumab." (PMID 25669984, 2015). "STAT3 is constitutively activated in several human cancers including skin, head and neck, ovarian, breast, colon, prostate and gastric cancer." (PMID 26186918, 2015). "We also determined the level of STAT3 proteinexpression in 3IB2 gastric cancer cells and found that 3IB2 cells exhibitedhigher STAT3 protein levels than 3I cells under serum-deprived conditions." (PMID 25928182, 2015). "Here we show that TGR5 is a suppressor of gastric cancer cell proliferation and migration through antagonizing STAT3 signaling pathway." (PMID 26417930, 2015).
gastric cancer (continued). "Our study provides evidence that STAT3 rs744166 G allele and infection with CagA-positive H. pylori with higher number of EPIYA-C segments are independent risk factors for gastric cancer." (PMID 26186918, 2015). "The aim of our study was to dissect the individual contributions of oncogenic signaling mediated by gp130 and IL-1RT1 ligands in IL-11/STAT3 mediated gastric cancer development." (PMID 25528766, 2015). "Previous studies showed that STAT3 was a key regulatory factor in gastric cancer development and that STAT3 activation promoted tumor cell survival and migration." (PMID 25646628, 2015). "In fact, mice with knock-in mutation located at Y757F on gp130, which destroys the docking site for SOCS3 that negatively regulates STAT3 activation, develop antral gastric cancer." (PMID 26186918, 2015). "Thesilencing of ASS1 expression in MKN45 and 3IB2 gastric cancer cells markedlydecreased STAT3 protein expression." (PMID 25928182, 2015). "When we examined STAT3 activation in human gastric cancer tissues, activation was detected in more than half of the adenocarcinoma tissues." (PMID 25785838, 2015). "It suggests that TGR5 antagonizes gastric cancer proliferation and migration at least in part by inhibiting STAT3 signaling." (PMID 26417930, 2015). "We identify that TGR5 is a suppressor of STAT3 signaling pathways in gastric cancer cells via suppressing STAT3 phosphorylation and its transcription activity." (PMID 26417930, 2015). "STAT3 activation has also been reported as a vital cause contributing to trastuzumab resistance in HER2+ breast and gastric cancer." (PMID 26474285, 2015). "Using bioinformatics, we identified STAT3 – a key transcription factor that plays a vital role in human gastric cancer angiogenesis – as a potential direct target of miR-874." (PMID 25596740, 2015). "The present data show that the inhibition of β-catenin and/or STAT3 suppresses gastric carcinogenesis, suggesting that these molecules are efficacious targets for the medicinal treatment of gastric cancer." (PMID 25331984, 2015). "Taken together,ASS1 regulates STAT3 signaling and plays an important role in the liver metastasisof gastric cancer." (PMID 25928182, 2015). "Dysregulation of the Janus kinase (JAK)/signal transducers and activators of transcription 3 (STAT3) signaling pathway is observed in many cancers including gastric cancers, and it correlates with both tumor progression and a poor prognosis." (PMID 26160167, 2015). "In conclusion, the present study shows that STAT3 rs744166 polymorphism and infection with H. pylori with CagA possessing higher number of EPIYA-C segments are independent risk factors for gastric cancer in the evaluated population." (PMID 26186918, 2015). "Initially, suppression of STAT3 and β-catenin expression was observed in the Gan mouse model of gastric cancer, and subsequent immunohistochemical analyses indicated suppression of STAT3 phosphorylation." (PMID 25331984, 2015). "Recent evidence indicates that IL-22 promotes gastric cancer development via activation of the STAT3 and ERK signaling pathways." (PMID 26160167, 2015). "Increased STAT3 pathway activation and TLR2 expression were also associated with poor survival in gastric cancer patients." (PMID 26064948, 2015). "JAK/STAT-mediated apoptosis can be found in gastric carcinoma, hepatocellular carcinoma, and colorectal cancer, especially through the phosphorylation of STAT3 to promote survival and inhibit apoptosis." (PMID 25588213, 2015). "Constitutive activation of STAT3 has also been demonstrated in human gastric cancer cell lines and in primary human gastric cancers." (PMID 25594045, 2014). "In summary, we have shown that WP1066 inhibits STAT3 dependent growth and blockade of apoptosis, both in vitro in human gastric cancer cells, and in vivo in an established mouse model of gastric tumourigenesis." (PMID 24804649, 2014).
gastric cancer (continued). "Here we show that WP1066 effectively inhibits STAT3 phosphorylation, and induces apoptosis in a gastric cancer cell line, and that it can inhibit gastric tumour growth in vivo by blocking induction of key STAT3-regulated genes." (PMID 24804649, 2014). "In this study we demonstrate that WP1066 dose-dependently inhibits the JAK2/STAT3 signaling pathway in human gastric cancer (AGS) cells, with a consequent 60% reduction in cell proliferation, and a smaller increase in apoptosis." (PMID 24804649, 2014). "Activated STAT3 is an established driver of human gastric cancer cell growth and proliferation, and prolonged activation of ERK1/2 induces apoptosis of gastric epithelial cells." (PMID 24804649, 2014). "In this study, we show that STAT3 phosphorylation is significantly increased in de novo and acquired trastuzumab-resistant breast and gastric cancer cells." (PMID 25327561, 2014). "A recent study also has shown that depletion of STAT3 in gastric cancer cells impairs microtubule polymerization due to a disruption of the interaction between STAT3 and Stathmin; as a result, cell migration and invasion were decreased." (PMID 24995504, 2014). "Together this data supports efforts to further develop and apply inhibitors of JAK2/STAT3 pathway as therapeutic agents for gastric cancer treatment." (PMID 24804649, 2014). "In gastric cancer, IL-26 activated STAT3 signaling induces up-regulated expression of Bcl-2, Bcl-XL and c-Myc, which leads to persistent cell proliferation." (PMID 24743778, 2014). "This is also true in human gastric cancer in which STAT3 activation by chronic phosphorylation at tyrosine (Y) reside 705 has been linked to increased growth, angiogenesis, invasion and metastasis of the primary cancer." (PMID 24804649, 2014). "Cell proliferation was significantly inhibited by P6, indicating that STAT3 activation in gastric cancer cells is involved in cell proliferation." (PMID 23593346, 2013). "Overall, our findings provide the first evidence that increased IL-6/STAT3 activation correlates with aberrant immunity, leading to the progression and invasion of gastric cancer." (PMID 24116074, 2013). "IL-6 has been shown to enhance invasion of gastric cancer cells through sustained activation of STAT3." (PMID 24116074, 2013). "The increased expression of STAT3 by immunohistochemistry was significantly correlated with the TNM stage of gastric cancer." (PMID 24116074, 2013). "It was found that the expreesion of STAT3 was increased in the foci of gastric cancer tissues as compared to its weak expression of STAT3 in adjacent normal mucosa." (PMID 24116074, 2013). "With these data in mind and other new studies on STAT3 signaling pathway, it is worth exploring a novel STAT3-targeted treatment for gastric cancer." (PMID 24116074, 2013). "Recently, STAT3 has been demonstrated to play a pivotal role in the maintenance of gastric cancer cells survival." (PMID 24116074, 2013). "While none of healthy controls was positively stained with phosphorylated STAT3, all cases of gastritis, gastric adenoma, gastric cancer, was positively stained for phosphorylated STAT3 in the epithelial cells." (PMID 23593346, 2013). "We demonstrated that fibroblasts produced IL-6 in response to gastric cancer cells through IL-1 signaling, and that IL-6 promoted tumor growth through STAT3 activation." (PMID 23593346, 2013). "Our results have also demonstrated that a more aggressive clinical behavior of gastric cancer with activated STAT3, such as more frequent large vessel invasion, and lower rates of complete resectability." (PMID 24116074, 2013). "Increased VEGF and survivin expression due to highly activation of IL-6/STAT3, helps gastric cancer cells to grow faster and to promote distant metastasis." (PMID 24116074, 2013). "Accumulating evidence indicates increased expression and activation of STAT3 in human gastric carcinoma." (PMID 24116074, 2013).
gastric cancer (continued). "Scheper and others have shown that inhibition of STAT3 activation can reduce survivin protein expression in gastric cancer and oral squamous cell carcinoma cell lines, and promote apoptosis of cancer cells." (PMID 23110625, 2012). "We further elucidated the effect of honokiol on the phosphorylation of STAT-3 in human gastric cancer cells (MKN45 and AGS) and HUVECs." (PMID 22937084, 2012). "Constitutive activation of STAT3 protein has been shown to prevent apoptosis and increase cell proliferation and metastasis in a number of cancers, including gastric cancer." (PMID 22662230, 2012). "Results indicate that NVP-BKM120, a pan-class I PI3K inhibitor, is able to inhibit mTOR downstream activation, but induces the phosphorylation of AKT and the activation of p-ERK or p-STAT3 in KRAS mutant gastric cancer cells." (PMID 22159814, 2012). "In this study, we found that during PI3K inhibition, AKT, ERK and/or STAT3 are activated as shown by the increased levels of phosphorylation in gastric cancer cells." (PMID 22159814, 2012). "The levels of PTEN, p-AKT, p-ERK and p-STAT3 were expressed to varying degrees in our panel of gastric cancer cell lines and p110α and p110β were expressed to similar degree in all cell lines." (PMID 22159814, 2012). "The results showed that honokiol markedly inhibited angiogenesis and peritoneal dissemination of gastric cancer cells via a calpain/SHP-1 interaction-activated STAT-3 dephosphorylation and VEGF down-regulation pathway." (PMID 22937084, 2012). "In the present study, we found that honokiol can effectively inhibit the phosphorylation of STAT-3 in HUVECs (both Tyr705 and Serine727 sites), human gastric cancer cells (Tyr705 site), and peritoneal metastatic tumors (Tyr705 site)." (PMID 22937084, 2012). "The baseline levels of p110α, p110β, PTEN, phosphorylated AKT, ERK, and STAT3 in human gastric cancer cell lines were measured by Western blotting." (PMID 22159814, 2012). "Honokiol markedly inhibited the increased DNA binding activity of STAT-3 in human gastric cancer cells." (PMID 22937084, 2012). "In the present study, we characterized the antitumor effects exerted by Class I PI3K single inhibition and combination with STAT3 inhibition in gastric cancer cell lines for the first time." (PMID 22159814, 2012). "We investigated the mechanisms of STAT3 activation and the function of STAT3 depending on its mechanism of activation in gastric cancer cells." (PMID 21730976, 2011). "We have here shown that STAT3 is activated at various levels in a subset of human gastric cancer cell lines." (PMID 21730976, 2011). "Activated MET thus appears to contribute to cell survival, at least in part, through the activation of STAT3 in MET-activated gastric cancer cells." (PMID 21730976, 2011). "Recent studies suggest that the IL-6/gp130/STAT3 (interleukin-6/glycoprotein 130/signal transducer and activation of transcription 3) pathway plays a role in the development of gastric cancer." (PMID 24212943, 2011). "Our data thus show that activated STAT3 contributes to either cell survival or motility in gastric cancer cells, and that these actions are related to different mechanisms of STAT3 activation." (PMID 21730976, 2011). "We first examined the baseline levels of total STAT3 and activated (Tyr705-phosphorylated) STAT3 in 12 human gastric cancer cell lines by immunoblot analysis." (PMID 21730976, 2011). "Studies have unraveled many aberrantly expressed genes in gastric cancer including BMI1, COX-2, HER3, RKIP and STAT3, SPARC and HER2, which make risk assessment of gastric cancer patients more accurately." (PMID 21933426, 2011). "Our unpublished data also proved that isoproterenol stimulated the expression of MMP-2 and MMP-9 in gastric cancer cells mainly through activating STAT3." (PMID 20939893, 2010).